TLR4 (toll like receptor 4)
Diseases named in the same sentence as TLR4 in open-access papers (continued):
Sharing a sentence is not in itself a finding about the gene and the disease.
pancreatic cancer (continued). "While the exosomes derived from pancreas cancer cells can downregulate the expression of TLR4 via miR-203, inhibiting the role of TLR4 in promoting angiogenesis in pancreatic cancer." (PMID 32565722, 2020). "In the murine models, the TLR4/MyD88 pathway can trigger protection from pancreatic cancer development or acting to promote inflammation and pancreatic cancer development." (PMID 33193429, 2020). "They revealed that pancreatic cancer-derived EVs containing miR-203 regulated the expression of TLR-4." (PMID 30634952, 2019). "Recent studies have shown that B7-H3 promoted metastasis and invasion of pancreatic cancer cells via the TLR4/NF-κB pathway." (PMID 31412888, 2019). "A previous study revealed that pancreatic cancer-derived EVs attenuated DC-mediated tumor suppressive responses initiated by TLR4." (PMID 30634952, 2019). "Pancreatic cancer-derived exosomes, for instance, can downregulate the expression of TLR4 (via miR-203) in DCs, inducing the production of TNF-α and IL-12 and inhibiting DCs-mediated antitumor responses triggered by TLR4." (PMID 29515996, 2018). "M2-polarized TAMs promote EMT in pancreatic cancer cells through Toll-like receptor 4 (TLR4)/interleukin-10 (IL-10) signaling." (PMID 28423676, 2017). "As TLR4 is the receptor for LPS, we investigated the expression of this receptor in pancreatic cancer cell lines." (PMID 28572836, 2017). "What is more, TEXs of pancreatic cancers were indicated to downregulate the toll-like receptor 4 (TLR4) expression in DCs via miRNA-203, thus reducing downstream cytokines TNF-α and interleukin-12 (IL-12)." (PMID 28642882, 2017). "M2 can promote epithelial-mesenchymal transition in pancreatic cancer cells, partially through TLR4/IL-10 signaling pathway." (PMID 26879926, 2016). "These experiments clearly indicate that TLR4/NF-κB signaling is essential for the sB7-H3-promoted progression of pancreatic cancer." (PMID 27273624, 2016). "In one report, enhanced TLR4 expression was identified in 69% of patients with pancreatic cancer and correlated with increased NF-κB signaling, enhanced hypoxia-inducible factor-1α (HIF-1α) expression, and dramatically reduced patient survival." (PMID 27941651, 2016). "TLR4 exhibited highest protein amounts in MIAPaCa-2 and SW1990 cells (next to AsPC-1 and Panc1) while BxPC-3 and primary pancreatic cancer cell lines PaCaDD135, PaCaDD159, and PaCaDD185 demonstrated only moderate TLR4 expression." (PMID 27941651, 2016). "Collectively, these results demonstrate that sB7-H3 promotes invasion and metastasis through the TLR4/NF-κB pathway in pancreatic carcinoma cells." (PMID 27273624, 2016). "In the present study, we demonstrate for the first time that sB7-H3 promotes the invasion and metastasis of pancreatic carcinoma cells through the TLR4/NF-κB pathway." (PMID 27273624, 2016). "Recently, the new role of TLR-4 in pancreatic cancer treatment has been reported." (PMID 40404908, 2025). "This discovery is highly consistent with recent studies on the pancreatic cancer microenvironment, which elucidated that LPS regulates macrophage polarization in a time-dependent manner through the TLR4/NF-κB pathway, culminating in a deeply immunosuppressive tumor microenvironment." (PMID 41235258, 2025). "Given the fact that ligation of Toll-like receptor 4 (TLR4) could potentially heighten inflammation in the pancreas, it can be postulated that the activation of TLR4 may play a pivotal role in the onset of pancreatic cancer." (PMID 38835055, 2024). "More importantly, L. casei & L. reuteri and TAK-242 exhibited nearly the same inhibitory effect on tumor growth and macrophage polarization, implying that L. casei & L. reuteri suppressed pancreatic cancer growth and M1 macrophage polarization by inhibiting TLR4." (PMID 37904102, 2023). "TLR4-induced secretion of IL-1β shaped the immunosuppressive microenvironment of pancreatic cancer." (PMID 37990304, 2023).
pancreatic cancer (continued). "B7-H3 is transcriptionally regulated by BRD4 in pancreatic cancer cells, and targeting the BRD4/B7-H3/TLR4 axis may be a novel therapeutic strategy to overcome chemotherapy resistance in pancreatic cancer." (PMID 36499340, 2022). "Acupuncture affecting pancreatic cancer through TLR4/NF-κB/IL-6/STAT3 pathway may be a potential method for the treatment of pancreatic cancer." (PMID 36105933, 2022). "Pancreatic cancer-derived sEVs induce ER stress-mediated apoptosis of T lymphocytes through the p38 MAPK pathway.Pancreatic cancer-derived sEVs downregulate TLR4 and downstream cytokines in dendritic cells(DCs) by miR-203, thereby inhibiting the immune response." (PMID 34980146, 2022). "Interestingly, HMGB1 reduced stemness features upon binding an alternative receptor, TLR4, suggesting a balance of TLR2/TLR4 expression can regulate pancreatic cancer stemness." (PMID 36118530, 2022). "Previous evidence reported that the proteolytic activity of these metalloproteinases is increased in pancreatic cancer cells co-cultured with M2-polarized macrophages in which the epithelial-mesenchymal transition (EMT) program is activated by TLR4/IL10 signaling pathway." (PMID 34884547, 2021). "Also in pancreatic cancer, TDEs express miR-203, which downregulate the expression of toll-like receptor 4 (TLR4), IL-12, and TNF-α in DCs." (PMID 33530529, 2021). "EVs from pancreatic cancer cells regulate TLR4 in dendritic cells via miR-203." (PMID 34623384, 2021). "Interestingly, these findings seem to contradict previous reports suggesting that TLR4 inhibition by triptolide can enhance the sensitivity of pancreatic cancer cells to gemcitabine by inhibiting the TLR4/NF-κB signaling." (PMID 34884547, 2021). "TLR4 may promote angiogenesis in pancreatic cancer tissues via activating the PI3K/AKT signaling pathway to induce VEGF expression." (PMID 34445616, 2021). "Another in vivo study on pancreatic cancer reported that, in DCs, cancer-derived exosomes down-regulate toll-like receptor 4 (TLR4) and downstream tumour necrosis factor-α (TNF-α) and interleukin-12 (IL-12) cytokines via miR-203, thereby decreasing DC expansion." (PMID 33669294, 2021). "Recently, a new role for TLR4 in pancreatic cancer progression has been reported." (PMID 34884547, 2021). "TLR4 upregulation is also involved in pancreatic cancer angiogenesis." (PMID 34884547, 2021). "The pro-carcinogenic activity of TLR4 in pancreatic carcinoma is still unclear." (PMID 34502140, 2021). "In addition, blockade of TLR4 through its specific siRNA or neutralizing antibody in the co-culture system of M2 TAM with pancreatic cancer cells abolished the TAM-increased mesenchymal markers in cancer cells." (PMID 32283687, 2020). "In turn, pancreatic cancer cells increased TLR4 expression in M2-polarized TAMs." (PMID 33224886, 2020). "Additionally, B7-H3 promoted the invasion and metastasis of pancreatic carcinoma cells via the TLR4/NF-κB pathway." (PMID 31412888, 2019). "In summary, TLR4 was expressed on all analysed pancreatic cancer cell lines." (PMID 28572836, 2017). "Studies demonstrated that M2-polarized TAMs promoted EMT in pancreatic cancer cells, suggesting a novel mechanism by which M2-polarized TAMs may contribute to the aggressive behavior of pancreatic cancer cells by TLR4/IL-10 signaling." (PMID 28970834, 2017). "As shown by RT-PCR, all of the investigated pancreatic cancer cell lines expressed TLR4." (PMID 28572836, 2017). "Whereas TLR4−/− mice showed decreased tumour growth in a murine model of pancreatic cancer, inhibition of MyD88 accelerated tumour development as well as an increased TLR4 expression correlated with tumour size, lymph node involvement, venous invasion and pathological stage." (PMID 28572836, 2017).
pancreatic cancer (continued). "Consistent with this, we provide experimental evidence for the first time in this study that priming of TAMs with TLR4 ligend (LPS) alone or in combination with IFN-γ not only recalibrates pancreatic tumor cells induced M2 polarization, but also confers anti-tumor potential in TAMs." (PMID 27511884, 2016). "To determine whether the inhibition of IL-8 and VEGF secretion via the TLR4/NF-κB pathway can suppress sB7-H3-mediated tumor metastasis in PCa cells, we performed in vivo experiments using a mouse model of spontaneous human pancreatic cancer lung metastasis." (PMID 27273624, 2016). "In addition, we found that sB7-H3 induces the expression of VEGF and IL-8, providing more evidence for the sB7-H3-induced invasion and metastasis of pancreatic carcinoma cells through the TLR4/NF-κB pathway." (PMID 27273624, 2016). "Therefore, we speculated that TLR4 inhibition by L. casei & L. reuteri in pancreatic cancer cells led to a decrease in IL-10 secretion, which in turn drove M1 macrophage polarization in TME." (PMID 37904102, 2023). "Besides, TLR4 is also involved in the immune escape of pancreatic cancer." (PMID 37904102, 2023). "Moreover, the regulation of TLR4 mediated by HIF-1α has been confirmed by knockdown experiments in which HIF-1α depletion is associated with inhibition of hypoxia-induced TLR4 overexpression and to pancreatic cancer regression." (PMID 34884547, 2021). "In the present study, we reported the detection of IL-1β-producing M2 polarised macrophages in pancreatic cancer, and revealed that their pro-inflammatory function could be further enhanced by IgG via crosstalk between the TLR4-TRIF and FcγRI/III-SYK signalling pathways." (PMID 31588122, 2019). "Upon treatment with miR-203-positive exosomes derived from pancreatic cancer cells, dendritic cells (DCs) downregulate toll-like receptor 4 (TLR4), tumor necrosis factor-α (TNF-α), and interleukin-12 (IL-12) expression, which may prevent DC antigen presentation." (PMID 30699928, 2019). "Furthermore, inflammation through TLR4 signaling promotes the development of immune suppressive microenvironment, such as recruitment myeloid-derived suppressor cells into local tumor environment, in breast, colon, renal cell, and pancreatic cancers." (PMID 29928275, 2018). "Toll-like receptor 4 may also contribute to the development of other cancers besides prostate cancer, including, but not limited to, liver cancer, reproductive organ cancer, pancreatic cancer, intestinal cancer, and skin cancer." (PMID 29928275, 2018). "In pancreatic cancer cells, soluble B7-H3 was found to induce the production of interleukin-8 (IL-8) and VEGF-A by upregulating TLR4 and NF-κB signaling pathways." (PMID 40214484, 2025). "TLR4 facilitated vascular endothelial growth factor (VEGF) expression through activation of PI3K/AKT signalling pathway, which ultimately promotes pancreatic cancer angiogenesis." (PMID 37904102, 2023). "The study showed that silencing of TLR4 decreased soluble B7-H3-induced activity of NF-κB and reduced the expression of IL-8 and VEGF in pancreatic cancer cells." (PMID 37112730, 2023). "The same authors also showed that TLR4 triggers angiogenesis by activating PI3K/Akt signaling, thereby inducing VEGF expression in pancreatic cancer cells." (PMID 36114448, 2022). "DCs downregulate TLR4, TNF-α, and IL-12 expression upon treatment with miR-203-rich exosomes derived from pancreatic cancer cells, which prevent DC-driven antigen presentation." (PMID 35501802, 2022). "Macrophage-derived cytokines and chemokines including IL1β, CCL18, and IL8 can promote the epithelial-mesenchymal transition of pancreatic cancer cells through various signaling pathways, including PAR1 and TLR4/IL10 activation." (PMID 34201127, 2021).
pancreatic cancer (continued). "Specifically, the stimulation of TLR4 and CAP1 receptors with Resistin, a hormone released by macrophages in the cancer microenvironment, activates the STAT3 pathway that confers to pancreatic cancer cells the ability to resist cancer therapy." (PMID 34884547, 2021). "Since a previous study suggested that SN extracts inhibited TLR-4 expression and the TLR-4 activation in macrophages, we also investigated the effects of SN extracts and/or gemcitabine on TLR-4 expression in human pancreatic cancer cells." (PMID 31521140, 2019). "In RT-qPCR, elevated relative gene expression of TLR2 (fold difference, FD = 29.8, p < 0.05), TLR4 (FD = 39.9, p < 0.005), and TLR9 (FD = 10.3, p < 0.005) was observed in pancreatic tumor tissues compared to normal tissues." (PMID 27941651, 2016). "A study on pancreatic cancer has shown that the expression of VEGF and Toll-like receptor 4 (TLR-4) has been positively correlated with the micro-vessel density and the pro-angiogenic activity within the tumor microenvironment (TME), a process involving the activation of the PI3K/AKT pathway." (PMID 35600385, 2022). "Our findings indicated that hPRDX5 effectively suppressed pancreatic cancer possibly via the TLR4-MAPK-NF-κB signaling cascade; hence hPRDX5 could be a prospective immunotherapy candidate for treating pancreatic cancer." (PMID 36102418, 2022). "TAMs can also directly support chemoresistance by secreting insulin-like growth factors (IGF)-1 and -2 which activate insulin/IGF receptors on pancreatic cancer cells, as well as Resistin, which binds to CAP-1 and TLR-4 on tumor cells and promotes gemcitabine resistance via STAT3 signaling." (PMID 34201127, 2021). "Subsequently, the stimulation of TLRs can actuate some adverse protumoral signaling pathways, such as TLR2, TLR4, and TLR9, which activate signaling pathways and anti-apoptotic Bcl-xL expression in terms of tumor cell activation and proliferation in pancreatic cancer." (PMID 33505964, 2020). "For example, disorders of innate antibacterial response are of fundamental importance in the development of gastrointestinal cancers, including pancreatic cancer, and increased expression of TRAF6, TLR4, and NOD1 are detected in peripheral blood leukocytes of pancreatic cancer patients." (PMID 30294322, 2018). "It was reported that miR-203 was present in pancreatic cancer cell derived exosomes, and miR-203 suppressed the expression of toll-like receptor 4 (TLR4) resulting in the decreased levels of tumor necrosis factor-α (TNF-α) and interleukin-12 (IL-12) in pancreatic cancer cell line Panc-1." (PMID 30046565, 2018). "Application of TLR4 siRNA and neutralizing antibodies against TLR4 and IL-10 expressed on M2-polarized TAM markedly inhibited E-cadherin reduction and the upregulation of Snail and vimentin in pancreatic cancer cells." (PMID 27191744, 2016). "Mechanistically, L. casei & L. reuteri inhibited TLR4 expression in pancreatic cancer cells, which ultimately promoted M1 polarization of macrophages in the TME; Meanwhile, L. casei & L. reuteri regulated gut microbial homeostasis and metabolite production in pancreatic cancer-bearing mice." (PMID 37904102, 2023). "This is supported by published work showing that blocking the TLR4/TNC interaction increased the anti‐PD‐L1 effects on metastasis inhibition and that combined treatment of anti‐PD‐L1 with AMD increased TIL infiltration reducing tumor growth in a pancreatic tumor model." (PMID 33988305, 2021). "proved that sB7-H3 first upregulated TLR4 expression, then activated NF-κB signaling, and finally promoted IL-8 and VEGF expression and demonstrated for the first time that sB7-H3 promoted the invasion and metastasis of pancreatic carcinoma cells through the TLR4/NF-κB pathway." (PMID 34349762, 2021). "Interestingly, TLRs seem to have a role in pancreatic cancer development, and TLR4 is explicitly highly expressed in human pancreatic cancer but not a healthy pancreas." (PMID 33193429, 2020).
pancreatic cancer (continued). "The synergism was independent of TLR-4 expression in pancreatic cancer cells." (PMID 31521140, 2019). "Similarly, although it was reported that HIF-1 could up-regulate TLR4 expression in pancreatic cancer cells under hypoxic conditions, to our knowledge this is the first report that HIF-1 can upregulate TLR3 and TLR4 in OSCC cell lines under hypoxia." (PMID 27191981, 2016). "Small interfering RNA (siRNA)-mediated knockdown of TLR4 or inhibition of TLR4/IL-10 signaling with neutralizing antibodies could reverse the EMT of the pancreatic cancer cells, suggesting that M2-polarized TAMs can promote EMT and aggressive behavior in pancreatic cancer cells." (PMID 35501802, 2022). "More recently, we described in advanced stage pancreatic cancers overexpressed TLR2, TLR4, TLR7, and TLR9 predominantly in tumor cells rather than tumor-infiltrating immune cells, making TLR inhibition strategies in this tumor even more interesting." (PMID 38390872, 2024). "Moreover, HMGB1-induced pancreatic cancer cells’ invasion and metastasis was mediated by the receptor for TLR2, rather than TLR4 or RAGE." (PMID 29615080, 2018). "To dissect the effects of TLR activation, we treated two of the established pancreatic cancer cell lines (BxPC-3 and MIAPaCa-2) and one primary pancreatic cancer cell line (PaCaDD135) with TLR specific ligands (LTA for TLR2, LPS for TLR4, ODN for TLR9) and a non-specific ligand (HMGB1)." (PMID 27941651, 2016).